IL6 (interleukin 6)
Diseases named in the same sentence as IL6 in open-access papers (continued):
Sharing a sentence is not in itself a finding about the gene and the disease.
COVID-19 (continued). "In that context, very recently it was reported that hospitalized COVID-19 patients receiving a single subcutaneous injection of the PCSK9-mAb evolocumab exhibited reduced death or need for intubation, as well as decreased inflammatory cytokine IL-6 levels in severe COVID-19 cases." (PMID 36851576, 2023). "In our cohort of severe COVID-19 patients, the prognostic value of CT scores seems, therefore, greater than basic clinical risk factors such as age, gender, CRP, or PaO2/FiO2 and comparable to laboratory biomarkers, such as IL-6 and IL-8." (PMID 37218940, 2023). "However, the overexpression of IL-6 can lead to respiratory dysfunction, poor outcomes, and mortality in COVID-19-infected patients." (PMID 36679421, 2023). "IL-6, previously thought to have proinflammatory function only, is recently recognized as potentially having both proinflammatory and anti-inflammatory roles in COVID-19 and diabetes." (PMID 37256676, 2023). "The slightly stronger increase of IL-6 serum levels post IVIg after COVID-19 vaccination could reflect a vaccine-specific immune response." (PMID 36929282, 2023). "Additionally, the direct proportional correlation between IL6 levels and OD conflicts with what has been reported in COVID-19 patients with OD." (PMID 37529051, 2023). "Even the cytokine interleukin-6 (IL-6), which has been shown to aid in risk stratification among adults with COVID-19, is not routinely ordered in pediatric cases." (PMID 37425266, 2023). "In severe COVID-19, IL-6 production and NLR values are also higher." (PMID 38099004, 2023). "Markedly elevated levels of Il-6 correlate with both the severity of COVID-19 and poor prognosis." (PMID 37373613, 2023). "IL-6 has been extensively studied in the context of COVID-19." (PMID 37515150, 2023). "Although IL-6 has been recognized as a marker and molecular target such as to justify the use of anti-IL-6 tocilizumab in patients with severe COVID-19, in post-COVID-19 there was only a trend of increasing IL6 levels during the early phase of recovery, which became more pronounced thereafter." (PMID 36836568, 2023). "Thus, during the first infection wave, IL-8 was significantly (p<0.05) increased predominantly in patients with severe disease versus those with moderate COVID-19 and a tendency in the same direction was observed for IL-6, IL-10 and IFN-α2." (PMID 36817433, 2023). "Serum ATX levels were correlated with levels of IL-6 and endothelial damage biomarkers, suggesting a relation between the ATX/LPA axis and hyperinflammation and associated vascular dysfunction in patients with COVID-19." (PMID 37189799, 2023). "Furthermore, a study conducted by Springall and collaborators revealed an intriguing association of IL-6, MMP9, and other cytokines with CD147, a molecule proposed as a potential entry point for the host receptor in COVID-19." (PMID 37764186, 2023). "Looking at the specific signaling map, certain molecular scenarios can be developed, where prospective HIF fluctuation in mild acute COVID-19 could be initiated by IL-6, and it may involve STAT3." (PMID 37301958, 2023). "However, IL-6 appeared to be further elevated at 18 months versus 3 months after acute COVID-19, 4.0 ± 4.6 pg/mL vs. 2.5 ± 2.6 pg/mL (p = 0.006), with 19.4% of participants having IL-6 levels above the normal range at 18 months after COVID-19." (PMID 36835948, 2023). "However, compared to patients with CRS, ARDS, sepsis, or even influenza, patients with COVID-19 have significantly lower serum IL-6 concentrations." (PMID 37649125, 2023). "In our present study, we aimed to demonstrate that cytokine levels could vary significantly among critically ill COVID-19 patients, using serum IL-6 levels as a surrogate marker." (PMID 37081872, 2023). "Therefore, the IL-6 blockade in COVID-19 is of vital importance and a global scientific call is needed to target the IL-6 blockade." (PMID 36769328, 2023).
COVID-19 (continued). "However, a longitudinal Swedish cohort study found that the “classical” IL-6 signaling pathway dominated in severe COVID-19 over the “trans-signaling” pathway." (PMID 38003780, 2023). "Inhibition of the expression of IL6 and monitoring of lymphocyte homeostasis may help prevent myocardial injury in COVID-19 patients." (PMID 37564653, 2023). "Large-scale clinical research is needed to emphasize IL-6 and COVID-19." (PMID 37960722, 2023). "This implies that IL-6 has a critical role in the pathophysiology of severe COVID-19." (PMID 38069327, 2023). "In the present study, we could show that serum IL-6 levels can also predict COVID-19 progression in a cohort of patients with a high proportion of hospitalized moderate cases." (PMID 37937220, 2023). "For instance, higher levels of the chemokine RANTES and cytokines IL-6 and IL-8 were observed in the bronchoalveolar lavage fluid (BALF) of individuals with alcohol use disorders, predisposing heavy drinkers to more severe COVID-19." (PMID 36986420, 2023). "In 2020, Coomes and Haghbayan published a systematic review and meta-analysis which revealed that COVID-19 patients with a complicated course of the disease have a 2.9-fold increase in serum IL-6 concentration compared to those with mild symptoms and good outcomes." (PMID 37371831, 2023). "Herein, as a proof-of-concept, we tested whether the modulation of the inflammatory response via IL-6 (colchicine), IL-17 (ixekizumab), and low doses of IL-2 could improve clinical outcomes of moderate to critical COVID-19 in hospitalized patients." (PMID 37075454, 2023). "Finally, this study used a cross-sectional design to explore the relationship between IL-6 levels and inner ear impairment in people who recovered from COVID-19." (PMID 36769761, 2023). "IL-6 is reported to have a unique role in the cytokine storm related to COVID-19." (PMID 37969879, 2023). "As a result, our study demonstrates how the type of taste alteration, which is correlated to the levels of inflammatory mediators such as IL-6, may serve as a prognostic indicator of the course of COVID-19." (PMID 35801415, 2023). "COVID-19 can lead to inappropriately increased production of cytokines such as IL6." (PMID 37043472, 2023). "Also, acute COVID-19 children had significantly elevated levels of cytokines, IFNγ, IL-2, TNFα, IFNβ, IL-6, IL-12, IL-17A and Granulocyte-Colony Stimulating Factors G-CSF in comparison to control children." (PMID 37013538, 2023). "Evidence is accumulating for the relevance of IL-6 as a prognostic marker in COVID-19." (PMID 37373677, 2023). "Although tocilizumab administration in COVID-19 is hypothesised that modulating IL-6 levels may reduce the duration or/and severity of COVID-19, suppression of the host immune response is considered a possible disadvantage of using this agent." (PMID 37322551, 2023). "The hypercytokinemia and T-cell hyperactivation of the high IL-6 group suggest that immunological features could differ among patients with critical COVID-19, despite similar clinical characteristics." (PMID 37081872, 2023). "As published earlier, IL-6 levels were significantly increased in more severe COVID-19 patients in both cohorts analysed, which subsequently could increase expression of MBL." (PMID 37051252, 2023). "In contrast, IL-6 showed a strong correlation with CT score for all participants with COVID-19 in this study, regardless of the variant." (PMID 37376606, 2023). "In particular, S24 was independently associated with ICU admission, indicating that a CT scan could improve prognostic stratification in hospitalized COVID-19 patients with progressive respiratory worsening and further treated with anti-IL-6 agents." (PMID 37218940, 2023).
COVID-19 (continued). "Patients with severe COVID-19 exhibit higher levels of pro-inflammatory cytokines (such as IL-6 and IL-8) in their bronchoalveolar lavage fluid as well as increased expression of inflammatory chemokines (such as CCL2) in macrophages compared to those with mild COVID-19." (PMID 36992366, 2023). "IL-6 is a pro-inflammatory cytokine, and anti-IL6 drugs have been approved by the FDA for COVID-19 patients having systemic inflammation or respiratory failure, as these conditions could be associated with an elevated release of cytokine." (PMID 37092446, 2023). "Notably, IL-6 is related to respiratory distress in human COVID-19 cases and was almost 600-fold higher in the single fatal AGM." (PMID 38133292, 2023). "IL-6, ARDS, and AKI are risk factors for mortality in children with COVID-19." (PMID 37889917, 2023). "We hypothesized that changes in IL-6 and D-dimers in severely affected COVID-19 patients are preceded by a distinct serologic signature that can be detected in patient sera 24–48 h in advance." (PMID 37834869, 2023). "However, IL-1 and IL-6 antagonists have potential adverse effects that have been reported with their use in COVID-19 treatment." (PMID 37046952, 2023). "The consumption of omega-3 fatty acids has been shown to lower markers of inflammation in serum, such as C-reactive protein, interleukin-6 (IL-6), interleukin-1β (IL-1β), and tumor necrosis factor-α (TNF-α), and other inflammatory factors that have been implicated in the cytokine storm of COVID-19." (PMID 37515117, 2023). "In spite of the well-known role of IL-6 in the cytokine storm induced by SARS-CoV-2 infection, no clear evidence has been presented on the role of IL-6 SNPs as susceptibility or protective factors in COVID-19." (PMID 36851291, 2023). "Considering that immunity and inflammatory responses are closely associated with the clinical manifestations of COVID-19 and outcomes, the levels of peripheral CD3+, CD4+, and CD8+ T cells as well as the levels of TNF-α, IL-6, and IL-10 were also determined in this study." (PMID 38249419, 2023). "In the context of COVID-19, cytokine storm in severe cases decreases endothelial cell antioxidant defense via downregulation of Nrf2, which may be IL-6-dependent." (PMID 37888066, 2023). "Although there are significant differences in terms of age, co-morbidities, and blood parameters, multivariate analysis still showed that the expression of MPO, ADA, CCL22, TNFα, and IL-6 mRNA in nasopharyngeal specimens is higher in COVID-19 patients when compared with the control group." (PMID 36482706, 2023). "The PPI network analysis exhibits that numerous genes, including IL-6, TNF-α, MAPK3, MAPK1, AKT1, mTOR, HIF1A, HSP90AA1, EGFR, CASP3, etc., are implicated in the pathogenicity of COVID-19 disease and also in the anti-COVID-19 effects of Meliae cortex’s key active phytonutrients." (PMID 36817449, 2023). "The treatments for COVID-19 have been limited and mostly supportive, but there has been growing interest in the use of IL-1 and IL-6 antagonists in the treatment of COVID-19 to reduce the severity of symptoms, improve the outcome of the illness, and potentially reduce the risk of death." (PMID 37046952, 2023). "Interestingly, only inflammatory IL-1β (P = 0.008) and IL-6 (P<0.05) showed significantly increased levels in long-COVID-19 compared to unexposed healthy individuals." (PMID 37018291, 2023). "However, in our analyses, only IL-6 and IL-10 were identified as representative of the Th2 profile in newborns of mothers with COVID-19." (PMID 36979888, 2023). "IL-6 is another cytokine that is elevated in COVID-19 patients and is thought to play a critical role in the cytokine storm observed in the severe cases of COVID-19." (PMID 37649897, 2023). "Therefore, sP2X7R besides being the only analyte significantly elevated at diagnosis in COVID-19 patients with fever and respiratory symptoms, is also an indicator predicting, on par with IL-6, progressive worsening of clinical conditions." (PMID 37215142, 2023).
COVID-19 (continued). "Similarly, female patients with acute COVID-19 also exhibited high levels of circulating IL-6 (127.64 ± 22.24 pg/mL) upon admission, which significantly decreased following the administration of 1α,25(OH)2D3 (1.84 ± 0.77 pg/mL)." (PMID 37375800, 2023). "Our findings suggest that IL-6 could be an important marker for classifying COVID-19 patients, even after the general population has been vaccinated, as all patients in our study were vaccinated." (PMID 37081872, 2023). "IL-6 is a potent activator of platelets, and hyperactive platelets that display faster aggregation, showing increased spreading on both fibrinogen and collagen has been observed in COVID-19 patient plasma." (PMID 36634048, 2023). "Our finding mirrors the findings of other authors who evaluated PCT and IL-6 in COVID-19 patients." (PMID 38129860, 2023). "The role of IL-6 in the pathophysiology of COVID-19-induced anosmia was discussed in a study by Netland and Collegues which pointed to encouragement in cytokines, especially IL-6, as a proinflammatory response in the brains of infected mice that changes neuronal signaling to cause anosmia." (PMID 36979225, 2023). "Our severe infant patients presented with elevated circulating IL-6 levels similar to those of adults with COVID-19, suggesting that high IL-6 levels might also constitute a signature of severe COVID-19 in children." (PMID 37047752, 2023). "Based on COVID-19 patient blood biomarkers and IL-6 production, this retrospective study supports the hypothesis that elevated levels of different biomarkers and IL-6 may reflect disease severity and clinical outcomes." (PMID 37896795, 2023). "Some studies indicated that IL-6 levels may be used to predict the occurrence of severe COVID-19, respiratory failure, or long-term neuropsychiatric symptoms of COVID-19." (PMID 36675242, 2023). "Correlation of interleukin-6 (IL-6) levels with the severity of COVID-19." (PMID 38099004, 2023). "Furthermore, the higher levels of IL-1β, IL6, IL-12p70, IL-17A, TNF-α, and IFN-γ are consistent with the inflammatory profile of COVID-19-associated lung injury." (PMID 38067158, 2023). "However, as with IL-6, results from trials of IL-1β blockade (eg, anakinra, canakinumab) in COVID-19 were also conflicting, potentially due to the timing of initiation and extent of inflammatory disease." (PMID 37427016, 2023). "However, among COVID-19 patients with disease progression, a significant increase in IL-6 levels from days 4 – 10 (397.65 ng/mL; IQR: 5.55 – 800.86) to days >14 (1248.50 ng/mL; IQR: 798.47 – 1698.52) from illness onset was observed (p < 0.05)." (PMID 36926338, 2023). "Elevated levels of interleukin-6 (IL-6) during the acute phase have prompted investigations into its role in long-term COVID-19 sequelae, suggesting that persistent inflammation could underlie the pathophysiology of Long COVID." (PMID 38131885, 2023). "We hypothesized that a distinct serologic signature precedes surges of IL-6/D-dimers in severely affected COVID-19 patients." (PMID 37834869, 2023). "A total of 22 serum samples from patients with COVID-19 (2 mild, 10 moderate, and 10 severe) were used to longitudinally evaluate IL-6 enhancement at Days 1, 5, and 10 after diagnosis, which corresponded to 3, 7, and 12 days after the onset of symptoms, respectively." (PMID 37896795, 2023). "The systemic cytokine profiles observed in patients with severe COVID-19 show similarity to those observed in activated macrophages, with increased production of IL-6 and IL-7, tumor necrosis factor (TNF), and the inflammatory chemokine CC–chemokine ligands CCL2 and CCL3." (PMID 37892134, 2023). "In the non-COVID-19 patients, the Roche IL-6 levels had a median (IQR) of 68 pg/ml (25.8–346.7)." (PMID 37650680, 2023). "Still, the COVID-19 vaccination may have resulted in higher levels of IL-6 at 18 months versus 3 months post-COVID-19 in some participants." (PMID 36835948, 2023).
COVID-19 (continued). "Inhibition of IL-6, a key mediator of the inflammatory process in CS and a prognostic marker in COVID-19, with IL-6 receptor inhibitors including tocilizumab and sarilumab has shown its efficacy in the severe COVID-19 stages." (PMID 37065291, 2023). "Furthermore, in line with the use of IL-6 inhibitors for treatment of COVID-19 patients attempting to mediate inflammation, IL-6 levels declined significantly in these patients on treatment." (PMID 36590898, 2023). "Our findings indicate that uPAR downregulation and the increased uPA levels in lung tissue of COVID-19 patients may substantially aggravate pulmonary fibrosis and lead to IL-6 and ACE2 upregulation." (PMID 36674896, 2023). "Lactiplantibacillus plantarum is a probiotic that was reported to modulate cytokine production by increasing TNF-α, IL-1β, IL-18, and IL-8, and reducing IL-6, a critical factor in immune dysregulation in COVID-19, thus enhancing the activity of natural killer cells." (PMID 37298539, 2023). "Elevated levels of serum interleukin 6 (IL-6) were observed in COVID-19 patients." (PMID 37376531, 2023). "Various proinflammatory cytokines are released in patients with COVID-19, especially IL-6." (PMID 35907817, 2022). "While, both IL-6 and IL-10, as well as serum IL-17A, showed an increasing trend in severe COVID-19 patients after one week of hospitalization suggesting that, in more severe patients, the inflammatory status and the release of cytokines is a more prolonged phenomenon." (PMID 35893398, 2022). "Besides, the use of IL-6 blocker (i.e. tocilizumab), and GM-CSF blocking were verified to be useful in a small proportion of severe COVID-19 patients by attenuating their hyper-inflammation and cytokine storm." (PMID 36069182, 2022). "COVID-19 is associated with cytokine storm with exaggerated inflammatory response characterized by release of large amounts of cytokines like IL-1b, IFN-α, IFN-γ, TGF-α, IL-6, IL-12, IL-18, and IL-33." (PMID 35382491, 2022). "Overproduction of inflammatory cytokines (so-called cytokine storm) is observed in the severe COVID-19 patients, as evidenced by elevated serum levels of proinflammatory cytokines (in particularly, interleukin-6 (IL6) and tumor necrosis factor alpha (TNF)), and C-reactive protein (CRP)." (PMID 36741372, 2022). "The few drugs which have received full approval from FDA to treat COVID-19 patients include the antiviral drug (remdesivir (VekluryTM)), 3CLpro protease inhibitor (Nirmatrelvir/ritonavir (Paxlovid)), IL-6 inhibitors (sarilumab, tocilizumab, and siltuximab), and the corticosteroid dexamethasone." (PMID 36278757, 2022). "IL-6 is also considered a predictor of progression to severe COVID-19, which endorses the hypothesis that IL-6 receptor antagonists could control the cytokine storm induced by SARS-CoV-2." (PMID 35371880, 2022). "These have shown increased Interleukin (IL)-6 and IL-8 production in severe cases COVID-19." (PMID 35204803, 2022). "We hypothesize that high-amplitude BCPAP may alter the natural history of COVID-19 ARDS by reducing IL-6, one of its chief mediators." (PMID 35239650, 2022). "We observed CCL2 and IL-6 overexpression in both severe and moderate COVID-19 groups that exceeded thousands of folds compared to controls, and these elevations were significantly higher in the severe COVID-19 group than in the moderate group." (PMID 35982898, 2022). "In patients who died of COVID-19, IL-6 levels were higher than in surviving patients." (PMID 35741174, 2022). "In a prospective study undertaken in 103 in-patients (mean age 66 years; 70% male) admitted to a hospital in Milan for severely symptomatic COVID-19, low 25(OH)D levels were negatively correlated with elevated levels of IL-6 and emerged as independent predictors of COVID-19 severity and mortality." (PMID 35276834, 2022).